DNMT1 (DNA methyltransferase 1)
Diseases named in the same sentence as DNMT1 in open-access papers (continued):
Sharing a sentence is not in itself a finding about the gene and the disease.
tumor (continued). "The tumor inhibitory capacity of miRNA-152 was linked to site-specific methylation of target genes, likely through increased expression of DNMT1 although further investigation is required to explore the effect of miRNA-152 across potential candidate genes." (PMID 34006907, 2021). "Taken together, these findings suggest that lower DNMT enzyme activity possibly caused by the heterogeneous DNMT1 variant in the KURC3 PDX tumor was associated with the acquired phenotype of temsirolimus resistance." (PMID 33107222, 2021). "This upregulation of tumor HLA-G involves inhibition of DNMT1 and demethylation of transporter associated with antigen processing 1 promoter." (PMID 34663641, 2021). "IL6-induced upregulation of DNMT1 was also found to result in hypermethylation and silencing of genes linked to tumor suppression, adhesion, and apoptosis, including PAI-1, IL-4, Maspin, and IRF-7." (PMID 34901003, 2021). "Our study identified the association between DNMT1 and ac-DNMT1 protein levels in tumor progression using a clinically annotated TMA." (PMID 34572918, 2021). "Given that the DNA methylation of tumor suppressors is mediated by DNMT1, the expression of DNMT-1 and its association with miR-338-5p-5p were examined." (PMID 34858853, 2021). "For further verification, gain‐of‐function and loss‐of‐function assays were performed to modulate DNMT1 expression in tumor cells, and then Nanog expression was evaluated." (PMID 32154082, 2020). "The degradation of DNMT1 depletes cellular functional DNMT1, causing DNA demethylation over cell cycles (passive demethylation) and inducing re-expression of silenced tumor-suppressor genes." (PMID 31370878, 2019). "DNA methylation plays a vital role in the cell, but loss-of-function mutations of the maintenance methyltransferase DNMT1 in normal human cells are lethal, precluding target identification, and existing hypomorphic lines are tumour cells." (PMID 29598829, 2018). "DNMT1 is the major enzyme that maintains the cellular DNA methylation levels but, in tumour cells, DNMT1 up-regulation is associated with cellular transformation in tumours presenting both global hyper- or hypomethylation." (PMID 28460463, 2017). "Further, downregulation of the DNA (Cytosine-5-)-methyltransferase 1 (DNMT1) gene that causes hypermethylation of various tumor-suppressor genes and leads to a poor prognosis in GBM, was detected." (PMID 29228563, 2017). "For example, miR-152-3p, which targets mRNA encoding DNA methyl transferase 1 (DNMT1) is a tumor suppressor, like the LncRNA called ADAMTS-AS2 (ADAM metallopeptidase with thrombospondin motif, antisense RNA 2), which also affects DNMT1 expression." (PMID 29261132, 2017). "DNMT1 has been associated with many tumor types and correlates with cell growth, apoptosis, aging, and death." (PMID 28380423, 2017). "IL-6 is mainly secreted by tumor-infiltrating lymphocytes and tumor-associated macrophages, explaining the increased expression of DNMT1 in the inflammatory stromal subtype." (PMID 27071379, 2016). "It was found that miR-152 was downregulated by HBx protein, causing an upregulation of its target DNA methyltransferase 1 expression and subsequently methylation of tumor suppressor genes to induce HCC42." (PMID 27138288, 2016). "Other studies in glioma have associated high expression of Dnmt1 and Dnmt3b with hypermethylation of tumor suppressor genes that regulate genomic stability and cell cycle, and influence cell tumorigenicity." (PMID 27158195, 2015). "The increase in DNMT1 activity causes aberrant methylation of the cellular genome, resulting in the silencing of tumor-suppressor genes and favoring cellular transformation." (PMID 24737381, 2014).
tumor (continued). "Overall, tumor cell DNA is hypomethylated compared to normal cell DNA and underexpression of Dnmt1 gene causes aggressive tumor induction in genetically engineered mice." (PMID 24255851, 2013). "We also found that curcumin-mediated down-regulation of DNMT1 was associated with reactivation of TSGs and tumor suppression, both in vivo and in vitro." (PMID 23457487, 2013). "Our data showed that DNMT1 expression was significantly associated with age and menopause state of the patients and with tumor localization." (PMID 22768205, 2012). "DNMT1 is the key maintenance methyltransferase in mammals and is responsible for both de novo and maintenance methylation of tumor-associated genes." (PMID 21962230, 2011). "Patients whose tumors had a DNMT1 expression level of 3 (high expression) had a 3.53 higher risk of recurrence than patients with lower scores of DNMT1 in the tumor." (PMID 21980391, 2011). "After adjusting for age, sex, ethnicity, smoking status, tumour grade, and clinical disease stage, we found that the high level of DNMT1 expression was associated with a 74% increased risk of death (HR, 1.74; 95% CI, 1.04–2.90)." (PMID 18414412, 2008). "Taken together, these results highlight the potential of epigenetic alterations in DNMT1 and DNMT3a, as well as the DNA mutations in DNMT3b, as epigenetic and genetic factors to neoplastic diseases of chickens." (PMID 18648519, 2008). "Moreover, dysregulation of ncRNAs is linked to epigenetic reprogramming throughout tumour advancement, primarily attributable to their capacity to engage with DNMTs, notably DNMT1." (PMID 40387409, 2025). "An intriguing relationship also exists between MAGE (Melanoma-Associated Antigen) proteins and DNMT1, which significantly influences gene expression and may play a critical role in tumor development." (PMID 39996888, 2025). "However, overexpression of miR-342-3p reduces the expression of its targets, DNMT1 and FoxM1, thereby inhibiting self-renewal-associated stemness phenotypes in vitro and suppressing tumor growth." (PMID 41226543, 2025). "Our observation somewhat aligns with the hypothesis that extensive alterations in the DNMT1-mediated DNA hypomethylation pattern are linked to a tumor-suppressive effect." (PMID 38755637, 2024). "Both mice with a heterozygous or homozygous loss of Dnmt1 (Math1-cre::Dnmt1Fl/+::SmoM2Fl/+ and Math1-cre::Dnmt1Fl/Fl::SmoM2Fl/+, respectively) showed a significant reduction in the number of proliferating tumor cells in the cerebellum at P5, as compared to Math1-cre::SmoM2Fl/+ mice." (PMID 39107797, 2024). "Recent papers have pointed out that DNMT1 catalyzes the promoter methylation of miR-148a in pancreatic cancer and acute myeloid leukemia; moreover, the aberrant expression of microRNAs is associated with tumor progression." (PMID 37304067, 2023). "For example, CDK4/6 inhibition was shown to enhance antigen presentation, which accompanied an increased IFNγ response; interestingly, the authors linked this outcome with downregulation of DNMT1, hypomethylation of TEs, and enhanced chemokine secretion that stimulated tumor immune surveillance." (PMID 37055433, 2023). "Along this line, our data demonstrates that high HCC UHRF1 causes increased tumor CSF1 production by reducing DNMT1-mediated DNA methylation in the CSF1 promoter; subsequently, tumor CSF1 promotes TAM tumor infiltration and boosts TAM COX-2 expression and PGE2 production." (PMID 35664070, 2022). "Similarly, it has been demonstrated that the increased expression level of DNMT1 was regulated by tumor-associated macrophages (TAMs), while the upregulated DNMT1 in turn aggravated GC via tumor suppressor gelsolin, that mediated epigenetic repression." (PMID 36091786, 2022). "It would be reasonable to speculate that the two investigated lncRNA variants may affect other targets through HIF1α and DNMT1 to reconcile the RNAs’ functions in tumor progression." (PMID 34493285, 2021).
tumor (continued). "Finally, in vivo tumor xenograft experiments were performed with nude mice to elucidate the effects associated with HOXA10-mediated HDAC1 regulation of DNMT1/KLF4 on the tumorigenic ability of LAD." (PMID 33596966, 2021). "So, DNMT1 mutation in the resistant tumor cells seemed to be homogeneous heterozygous mutation." (PMID 33107222, 2021). "Also, over-expression of DNMT1 was considered to be an independent prognostic factor which showed a 2.385 times higher risk for the tumor to relapse in comparison to a lower expression level." (PMID 33369458, 2020). "V600EBRAF is associated with hypermethylation of various tumor suppressor genes which might be due to increased DNMT1 expression and upregulation." (PMID 29179510, 2017). "Since LSF association with DNMT1 resulted in activation of DNA methylation, we speculate that interaction between both may trigger hypermethylation of CpG islands containing tumor suppressor genes." (PMID 27845898, 2016). "High tumor expression of DNMT1 was associated with shorter OS in univariate analysis (p = 0.041)." (PMID 27071379, 2016). "Consequently, the genome instability and tumor susceptibility associated with reduced Dnmt1 and DNA methylation are caused in part by impairment of MMR functioning." (PMID 27886214, 2016). "In addition, increased expression of DNMT1 has been found in several tumour types including lung and caused silence of tumour suppressor genes 8–10." (PMID 25598321, 2015). "The data showed that the tumors in the pcDNA-DNMT1 transfection group were smaller than those in the negative control+TMZ group on days 13–21, whereas the reduced tumor growth associated with DNMT1 overexpression was abrogated by treatment with the miR-20a mimic." (PMID 26337869, 2015). "Tumor hypoxia represents another possible cause of DNMT1 depletion." (PMID 26504497, 2015). "The removal of DNMT1 from the replication site can be a reason for global genomic hypomethylation and decrease in promoter methylation of certain genes that encode proteins important for cycle regulation and tumor suppression." (PMID 26703571, 2015). "Several studies demonstrated that DNMT1 is overexpressed in human PCa tissues, compared to normal prostate, leading to deleterious inactivation of tumor-suppressor genes and might be associated with tumor progression and poor prognosis." (PMID 24797896, 2014). "Our results suggested that the aberrant methylation profiles of DNMT1 and DNMT3a as well as CpG to TpG transitions in DNMT3b are complex epigenetic and genetic factors that may be involved with neoplastic disease susceptibility or resistance in chickens." (PMID 18648519, 2008). "Taken together, genetic targeting of Dnmt1 in ECs strikingly inhibits tumor growth despite subtle changes in vessel morphology and moderate reductions in vessel branch length; we therefore considered secondary mechanisms whereby loss of Dnmt1 in ECs could impair tumor progression." (PMID 37055433, 2023). "Additionally, it has been demonstrated that the active features of BC-associated fibroblasts cells, major components of the tumor microenvironment, could be normalized through drug targeting of DNMT1/DNMT3A and the consequent modulation in gene methylation." (PMID 36091786, 2022). "To test whether the observed up-regulation of DNMT1 expression in ALK tumor samples is associated with deregulation of cell cycle–associated genes, we performed Western blot analysis using antibodies against c-MYC, CDK4/CDK6, cyclin D1, and the proliferation marker PCNA." (PMID 33310759, 2021). "The results showed that the expression of TYMS was negatively correlated with tumor mutational burden and microsatellite instability, and positively correlated with the expression of four methyltransferases (DNMT1: red, DNMT2: blue, Dnmt3A: green and DNMT3B: purple)." (PMID 35003215, 2021).
tumor (continued). "Moreover, EZH2 and DNMT1 are negatively associated with tumor-infiltrating CD8+ T cells." (PMID 33031059, 2020). "Since upregulated expression of CDK2, CCNE, DNMT1 is associated with accelerated cell cycle progression and thus tumor growth these results suggest that the tumors might have started to develop a drug resistance after initially responding to the treatment with gemcitabine." (PMID 31661013, 2019). "Notably, the epigenetic modifiers TET1 (chromosome 10) and DNMT1/3B (chromosomes 19 and 20) were haploid and polyploid in tumour respectively, which suggests a connection between the observed hypermethylation (DNMT polyploidy) and 5hmC loss (diminished TET function) in the tumour." (PMID 29263824, 2017). "Over-expression of DNMTs has been described in several human tumour types, including lymphomas, liver, prostate, colorectal, breast, lung, pancreatic and endometrial cancer, and is generally associated with a more aggressive phenotype, indicating that DNMT1, 3A and 3B likely act as oncogenes." (PMID 27764816, 2016). "Therefore, whether over-expression of DNMT1 accounts for the only or key causes of hypermethylation of tumor suppressor genes remains to be confirmed." (PMID 21999220, 2011). "Depleting CD4+ T cells, or blocking lymphocyte egress from the lymph nodes, rescues tumor growth in mice with conditional deletion of Dnmt1 in ECs (Dnmt1iECKO) and dramatically shortens overall survival, whereas NK cells are dispensable." (PMID 42156591, 2026). "DNA methyltransferase 1 (DNMT1) is proposed as a direct target of miR‐217, whereas inhibition of DNMT1 activity effectively suppresses tumor growth." (PMID 40909350, 2025). "In summary, our study reveals that DNMT1‐mediated methylation of the CBX7 promoter region leads to the downregulation of CBX7 expression in PDAC, which is significantly associated with tumor clinical staging." (PMID 40387566, 2025). "They concluded that miR‐484 was reduced due to DNMT1‐mediated hypermethylation occurring in its promoter region, and this molecular event contributes to its role as a tumour suppressor in CC." (PMID 40387409, 2025). "NNMT and DNMT1 jointly maintain the sensitivity of tumor cells to oxidative phosphorylation inhibitors." (PMID 40842594, 2025). "Mechanistic investigation disclosed that LUCAT1 plays a role in modulating the stability of DNMT1, leading to the inhibition of tumour suppressor gene expression via DNA methylation." (PMID 40387409, 2025). "The paucity of tumor DNMT1 decreases and p16 re-expression are consistent with the lack of clinical response." (PMID 41428220, 2025). "In oral squamous cell carcinoma (OSCC), cerivastatin and simvastatin have been shown to significantly suppress DNMT1, a key enzyme responsible for maintaining promoter hypermethylation of tumor suppressor genes." (PMID 40746725, 2025). "They finally disclosed that pretreatment with pcDNA‐DNMT1 suppressed the growth of U251/TM xenograft tumours, while pretreatment with DNMT1‐small hairpin RNA enhanced their growth." (PMID 40387409, 2025). "Targeting DNMT1 in immunocompetent mouse models significantly elevated CXCL12 expression in tumours, resulting in a robust immune response and the eradication of early lung metastases." (PMID 40442778, 2025). "A growing body of evidence suggests that aberrant methylation of tumor suppressor genes is mediated by overexpression of DNMT1." (PMID 40003580, 2025). "Given the frequent overexpression of DNMT1 in various malignancies, these findings highlight a promising epigenetic mechanism for statin-mediated tumor suppression." (PMID 40746725, 2025). "We found that the DNMT1 activity (determined as the ΔCT value of qPCR) exhibited a significant correlation with tumor stage." (PMID 40317882, 2025). "‐Genistein reduces global DNA methylation‐Inhibits DNMT1 activity and blocks cytosine entry‐Reactivates tumor suppressor genes via promoter demethylation." (PMID 41146399, 2025).
tumor (continued). "Hepatocyte growth factor, one of the essential growth factors in the HCC microenvironment, represses tumor suppressor genes via DNMT1‐mediated DNA hypermethylation." (PMID 40761482, 2025). "DNMT1, which restores specific methylation patterns to hemimethylated strands during replication, plays a crucial role in tumor cell growth, migration, and invasion." (PMID 40317882, 2025). "In vivo, miR‐217 overexpression suppressed tumor growth, downregulated DNMT1 and GLI1, and increased apoptosis." (PMID 40909350, 2025). "Evidence indicates that silencing DNMT1 expression reduces tumour cell proliferation and migration, while its overexpression promotes malignant behaviour." (PMID 40806634, 2025). "In this manner, their findings propose an innovative regulatory pathway involving miR‐148a/152 and DNMT1, highlighting the tumour suppressive roles of miR‐148a and miR‐152 by targeting IGF‐IR and IRS1." (PMID 40387409, 2025). "DNMT1 inhibitors can demethylate hypermethylated regions of tumor-suppressor genes and other regulatory genes, whose silencing contributes to malignant transformation." (PMID 39996888, 2025). "As the tumor stage increased, a pronounced and significant elevation in DNMT1 activity was revealed." (PMID 40317882, 2025). "MSP and ChIP assays were conducted to assess the impact of DNMT1 on the methylation of the TSHZ2 promoter in tumor tissues." (PMID 40909350, 2025). "Through its role in promoting epigenetic silencing of tumor suppressor genes, DNMT1 facilitates tumor growth and invasion, underscoring its potential as a critical driver of PDAC malignancy." (PMID 40387566, 2025). "Pancreatic CSCs, irrespective of their heterogeneity or polyclonality within the analysed tumours, exhibit elevated levels of DNMT1 activity and DNA methylation." (PMID 40387409, 2025). "For example, persistent IL-6/STAT3 signaling within the tumor microenvironment induces DNMT1 and EZH2 expression, thereby reinforcing the epigenetic repression of tumor suppressor genes and maintaining a pro-oncogenic inflammatory state." (PMID 41226277, 2025). "circ-Dnmt1, frequently upregulated in malignant breast cells, promotes autophagy and supports tumor survival; its inhibition reduces cell proliferation and tumor growth in vivo." (PMID 41516015, 2025). "Clofarabine blocks the proliferation of tumor cells by decreasing DNMT1 and inhibiting the methylation of TSGs, such as PTEN, antigen-presenting cells (APC), and RARβ2." (PMID 40650308, 2025). "Emerging evidence demonstrates that AID engages in multifaceted transcriptional regulation through collaborative interactions with epigenetic modifiers such as DNMT1 and TET2, particularly modulating tumor-associated gene networks." (PMID 40270606, 2025). "For example, upregulation of DNA methyltransferase DNMT1 can induce hypermethylation of key tumor suppressor genes, such as p16^INK4a, thereby promoting tumor progression." (PMID 40396172, 2025). "Patients who had a more advanced tumor stage (pT) more frequently exhibited an overexpression of DNMT1 and G9a." (PMID 39810240, 2025). "Instead, DNMT1 is often overexpressed in BC metastatic stages, indicating its involvement in tumor spreading in other organs or tissues, especially of TNBCs." (PMID 40141248, 2025). "Research has established that activated STAT3, through its interaction with DNA methyltransferase 1 (DNMT1), can enhance the CpG island methylation of several tumor-suppressor genes, thereby contributing to their silencing." (PMID 40083697, 2025). "Another emerging agent, CM-272, is a dual inhibitor targeting DNMT1 and G9a, offering a synergistic epigenetic blockade and demonstrating robust anti-tumor activity in hematologic malignancies and immune-responsive solid tumors." (PMID 41335282, 2025). "Overexpression of DNMT1 is essential for silencing tumor suppressor genes via promoter hypermethylation." (PMID 39796183, 2025).